CD4 (CD4 molecule)
Diseases named in the same sentence as CD4 in open-access papers (continued):
Sharing a sentence is not in itself a finding about the gene and the disease.
tumor (continued). "Our study improved the mechanism of FOXP3-TSDR hypomethylation in tumor-infiltrating CD4+ T cells of CRC patients." (PMID 30013992, 2018). "In tumor-bearing animals, treatment with methyl gallate delayed tumor progression and prolonged survival through inhibition of the tumor infiltration of CD4+CD25+ Treg cells." (PMID 29785194, 2018). "CD4+ T cells from tumours demonstrated significantly decreased methylation compared to LN (p < 0.05) and PBMCs (p < 0.0001)." (PMID 30075815, 2018). "We then analysed the effects of Y27632 on tumour growth in the CT26.CL25 tumour model in which CD4+ or CD8+ T cells were depleted by intraperitoneal injection of a neutralizing antibody." (PMID 29867097, 2018). "As tumor-directed CD4 and CD8 T lymphocytes belong to the adaptive arm of the immune system they can only develop in dependence on their corresponding antigens." (PMID 29032503, 2018). "This signature CpG was significantly hypomethylated in CD4+ T cells from lymph nodes (p < 0.05) and tumours (p < 0.01) compared to PBMC." (PMID 30075815, 2018). "Elderly patients intended to have a lower level of CD4+/PD-1− tumor-infiltrating lymphocytes (p < 0.05)." (PMID 30069490, 2018). "We consider that CD8+ CTLs are necessary for tumor regression and CD4+ helper T cell responses play a pivotal role in activating these CD8+ CTLs in this vaccine models using miPSDCs expressing CEA3,31." (PMID 29545628, 2018). "After 24 h of in vitro restimulation, we predominantly detected CD4+ T cells with a Th1 profile, in both hCT26 tumor-bearing (TB) and tumor-free (TF) vaccinated groups, secreting IFN-γ, IL-2, TNF-α, and GM-CSF." (PMID 30483475, 2018). "Such antigen-capturing nanoparticles substantially increased the ratio of tumor-infiltrating effector CD8+ T cells to regulatory CD4+ T cells." (PMID 30013560, 2018). "Consistent with the human in vitro data, dexamethasone increased the percentage of CTLA-4-expressing CD4 T cells of tumor-bearing mice in a dose-dependent manner." (PMID 29891009, 2018). "The tumor from this patient had fewer than 30 somatic mutations and the BRAF V600E specific CD4+ T cell response was correlated with robust and persistent CD8+ T cell responses to multiple self–antigens." (PMID 30400835, 2018). "IL-2’s high potency for activation of CD4+ regulatory T cells (Tregs) that suppress T cell-mediated tumor killing responses further reduces its therapeutic window." (PMID 30400822, 2018). "NSCLCs showed increased CD4+/CD8+/CD20+ TILs with higher expression of functional markers than case-matched non-tumor lung tissue." (PMID 30400835, 2018). "Numerous studies have highlighted the contribution of tumour-reactive CD4+ T cells to cancer immunotherapy efficacy." (PMID 30001747, 2018). "Compared with non-NCT-SCCs, NCT-SCCs showed significantly higher densities of CD3 + CD4+ (P = 0.019) and PD-1+ (P < 0.001) cells in the tumor epithelial compartment." (PMID 29871672, 2018). "CD4+ T cells play a central role in anti-tumor responses and empower tumor-specific CD8+ T cells to gain their full cytotoxic phenotype." (PMID 29546435, 2018). "Upregulation of MHC class II on autologous tumor cells stimulated CD4+ TIL to produce both IFN-gamma (4.0%) and TNF-alpha (5.9%)." (PMID 30400835, 2018). "The tissue density maps and GSEA together suggest effector CD4+ T-cells are present in the tumour microenvironment." (PMID 30219078, 2018). "The effect of OV therapy on distant tumors has been studied with Newcastle disease virus (NDV) and was shown to be immune-mediated through an increase in tumor-specific CD4(+) and CD8(+) T-cells." (PMID 29699566, 2018). "First, we found that CD4+ TGF‐β CAR‐T cells significantly reduced the ability of TGF‐β to impair the cytotoxicity of tumor‐targeting CD8+ T cells." (PMID 30065964, 2018). "CD4+ Tregs preferentially migrated to tumor and ascites and were rarely found in draining lymph nodes at later cancer stages." (PMID 30042343, 2018).
tumor (continued). "Two main types of Treg are natural Treg (nTeg) that are thymus-derived and induced Treg (iTreg) arising from conversion of conventional CD4+ T cells exposed to tumor-derived factors." (PMID 29682521, 2018). "At day 10 of tumor growth, the MIF-deficient tumors contain significantly more IFNgamma-producing CD8+ and CD4+ T cells." (PMID 29864117, 2018). "The densities of CD8+ and CD4+ immune infiltrates in the tumor parenchyma and tumor mesenchyme were assessed by IHC and multi-color IF analyses." (PMID 30285868, 2018). "In the IL13 locus, the CD4+ T cells demonstrated an increased methylation in muscle invasive pT2 tumours compared to the cells from patients with pT0 stage." (PMID 30075815, 2018). "In mice that did not receive ALX148, staining with labeled ALX148 revealed greater CD47 expression on tumor cells than on CD4+ cells from the spleen or tumor." (PMID 30133535, 2018). "Tumor antigens captured by APC activate CD4 helper and cytotoxic lymphocyte-driven immune responses for tumor regression." (PMID 29780392, 2018). "B cells also play a role as antigen-presenting cells, generating tumor-associated antigen-specific CD8+ and CD4+ T cells, pointing to crosstalk between B and T cells in anti-tumor immunity." (PMID 29844447, 2018). "If transferred adoptively, CD4+ T cells can even rescue anergic tumor infiltrating CD8+ T cells by T cell help." (PMID 30214445, 2018). "It was further determined that the DN hepatic iNKT cells were significantly better at tumor rejection compared to the CD4+ hepatic iNKT cells." (PMID 29973936, 2018). "With regard to the mechanisms of anergy and pTreg induction, depletion of host Tregs inhibited conversion of naive tumor Ag-specific CD4+ T cells into pTregs and restored a typical effector phenotype, ultimately promoting their accumulation in the tumor bed." (PMID 29844317, 2018). "This is due to factors that hamper the immune response against cancer such as the presence of the suppressive regulatory CD4 T cells (Tregs) in the tumor microenvironment." (PMID 30460193, 2018). "IL-12-LNP elicited marked infiltration of activated CD44+ CD3+ CD4+ T helper cells into the tumor, and increased the production of Interferon γ (IFNγ)." (PMID 30458889, 2018). "Cdk5 was thus necessary for PD-L1 upregulation after IFN-γ stimulation through STA1/IRF1 axis and its disruption led to tumor rejection in a CD4 + T-cell-dependent manner in medulloblastoma mouse models." (PMID 29765155, 2018). "In several different cancer models, transfer of Th17-polarized cells enhanced survival and tumor regression superiorly to Th1 or unpolarized CD4+ cells." (PMID 30140266, 2018). "To understand the relative contribution of CD4+ TH cells and CD8+ TC cells in controlling tumor growth and metastasis, we depleted either CD4+ TH cells or CD8+ TC cells from the control mice." (PMID 30237863, 2018). "Tumor-infiltrating lymphocytes (TIL), like natural killer (NK) cells, CD8+ cytotoxic T cells and CD4+ T helper (Th) cells have all been found to promote anti-tumor immunity." (PMID 29671006, 2018). "And TCM leads to increased CD4/Foxp3+ ratio in tumor bed by enhancing recruitment and chemotactic migration of T cell." (PMID 30139382, 2018). "In fact, the ratio of CD4+ effector to Treg cells in mPD1-Fc-OX40L treated mice was 2–3-fold higher than antibody combinations in the tumor and ~ 1.5-fold higher in the spleen." (PMID 30563566, 2018). "After destruction of tumor cells dendritic cells engulf cellular debris and present tumor antigens to T-cells that leads to the activation of CD4+ and cross-priming of CD8+ T-cells." (PMID 29849947, 2018). "Immunohistochemistry on tissue microarrays (TMA) was performed to demonstrate expressions of PD-L1, HIF-1α, and HIF-2α in tumor cells and PD-1, CD4, and CD8 in lymphocytes to assess lymphocyte density in tumor microenvironment." (PMID 30144808, 2018).
tumor (continued). "Instead, PD-L1 expression in tumor cells and its interaction with PD-1, CD4, CD8-positive lymphocytes was our center of interest." (PMID 30144808, 2018). "In both mouse models and human patients, the function of predicted neo-antigens have been verified,by measuring CD4 T cell responses or tumor rejection." (PMID 30075702, 2018). "Our data suggests that CD4+ T-cell subsets other than Tfh cells are present in the tumour microenvironment of MZL warranting further studies characterising these and establishing their biological and clinical significance." (PMID 30219078, 2018). "In general, it has been shown that the presence of tumor-specific CD4 T cells enhanced recruitment, proliferation, and effector functions of CD8 T cells by IFN-γ-dependent production of chemokines and IL-2." (PMID 29032503, 2018). "Decreased tumorigenesis occurred together with elevated production of chemokines in tumor cells and increased IFNγ-producing CD8+ and CD4+ (Th1) T lymphocytes in the tumor microenvironment." (PMID 30622432, 2018). "Nonetheless, suppression of tumor growth was achieved only by anti-PD-1, or the combination of anti-PD-1 with the agonistic antibody anti-4-1BB, as well as by anti-CD4 mAb monotherapy." (PMID 29348598, 2018). "Upon further examination, it was discovered that CD4+ iNKT cells were the primary source of IL-13, creating an immunosuppressive environment that prevented tumor rejection." (PMID 29973936, 2018). "Tumor-specific epitopes for each patient included CD4, CD5, and CD25, based on available histo-/cyto-pathology results." (PMID 30400835, 2018). "It has also been observed that IL-4 secreting CD4+ T lymphocytes were able to indirectly promote tumor invasiveness and pulmonary metastasis of mammary tumors via enhancing pro-tumor properties of tumor associated macrophages." (PMID 30356678, 2018). "Further interrogation of this phenomenon revealed that EMT6 tumors, even in the absence of M7824 treatment, are highly susceptible to CD4 depletion, as 90% of PBS-treated mice underwent complete tumor rejection when CD4+ T cells were depleted." (PMID 29721396, 2018). "Tumor growth was dramatically suppressed in mice administered CD4+ cells where lnc-INSR had been knocked down." (PMID 30310051, 2018). "Fluorescent activating cell sorting (FACS) analysis of leukemic cells revealed an immature CD8+CD4+/− cell surface phenotype with Lmo2 expression in the tumor T cells and clonal immature T‐cell receptor (TCR) rearrangement." (PMID 29880602, 2018). "As such, lung and tumor derived CD4+ and CD8+ T cells can be divided into three populations based on the expression of CD69 and CD103 (CD103+CD69+, CD103−CD69+, and CD103−CD69−)." (PMID 30505306, 2018). "RNA-seq of single cell T cells sorted from hepatocellular carcinoma samples identified an easily distinguished CXCL13+ CD4+ T cell population isolated from tumor tissue." (PMID 30190721, 2018). "The liposome-encapsulated SLPs efficiently induced functional antigen-specific CD8+ and CD4+ T cells, and were able to induce T cell mediated tumor regression and immunological protection in two different tumor-bearing mouse models." (PMID 30209623, 2018). "The combination of 17-AAG and Tyrp1-specific CD4+ T cells treated mice showed significantly higher survival at Day 40 after tumor challenge when compared with Tyrp1-specific CD4+ T cells alone (P<0.05)." (PMID 29481571, 2018). "In tumor immunity, effectors cells such as NK cells, and CD4+ and CD8+ cells are in competition with Treg cells, because Treg cells strongly inhibit effector cells that mediate antitumor immunity." (PMID 29662489, 2018). "It is noteworthy that when an α-PD-1 was added to cocultures of naïve immune lineages and pMMR tumour cells, an increase in CD4+ cell proliferation was observed, suggesting that the T-cell exhaustion mechanism due to PD-L1/PD-1 crosstalk had been abolished." (PMID 30285662, 2018).
tumor (continued). "The recruitment of CD8+ T-cells into the tumor was more marked in mice where tumor growth was suppressed by the anti-PD-1/4-1BB mAb combination or by anti-CD4 alone." (PMID 29348598, 2018). "Taken together, these studies show the complex regulation of immune responses by CD4 T cells that mediate antitumor immunity or promote tumor growth, depending on the context and the applied regimens." (PMID 29032503, 2018). "Although not meeting significance, this is likely to be the result of the improved efficacy of intra-tumoral Treg cell depletion observed for IgG1SDALIE relative to wild-type IgG1 and consequent higher production of IFNγ by CD4+eff T cells in the tumor." (PMID 29576375, 2018). "Here the authors use a mouse genetic tumor model to show that tumor-specific CD4 T cells can become anergic or suppressive in the draining lymph node to modulate tumor immunity." (PMID 29844317, 2018). "Neoadjuvant chemotherapy seemed to result in a relocation of Th1-committed CD4+ T cells from blood, presumably to the tumour, indicated by shifts in the methylation patterns, whereas no such shifts were seen for lineages corresponding to IL13, IL17A and FOXP3." (PMID 30075815, 2018). "Highest IFN-γ secretion was measured for both tumor cell lines when PTM-transduced CD4+ and PTM-transduced CD8+ were combined." (PMID 30214445, 2018). "One explanation is the increased infiltration of the WT1-specific effector CD8+ T cells via enhancement by WT1-specific CD4+ T cells of their homing into the tumor from outside." (PMID 30542516, 2018). "Only CD4+ T cells among the tumor infiltrating CD45.1+ immune cells were statistically higher in mice treated with the WT1 combination vaccine than in those treated with the WT1 CTL vaccine alone." (PMID 30542516, 2018). "With regard to Tregs, the FOXP3 signature locus was significantly demethylated in CD4+ T cells from the tumour compared to PBMCs (p < 0.001)." (PMID 30075815, 2018). "Herein, we will examine the role of CD4+ T cells in tumor immunity, new discoveries of potent subsets within the CD4+ lineage, and clinical implications of engineering human CD4+ T cell subsets with CAR-specificity to extend treatment outcomes." (PMID 30140266, 2018). "The ratio between effector CD8+IFNγ+ and CD4+IL-4+ T cells, the latter commonly endowed with a pro-tumor ability, was tipped in favour of effector cells in the SULT2B1b-4T1 TME." (PMID 30333826, 2018). "For example, the depletion of α-SMA+ CAFs in pancreatic cancer accelerates tumor growth, induces immunosuppression by increasing the number of CD4+Foxp3+ Tregs in tumors and reduces survival." (PMID 29545811, 2018). "To further focus on the site of enrichment of each CD8+ T cell clone following anti-CD4 mAb treatment, we analyzed the frequency of each overlapping clone in the tumor or dLN CD44hi." (PMID 30733724, 2018). "Antigen presenting cell- (APC-) derived extracellular vesicles carry tumor antigens in vivo, which can inhibit tumor cell growth by stimulating CD4+ and CD8+ T cells." (PMID 29850495, 2018). "It is well established that PD-L1 expression is up-regulated in solid tumors where it can provide direct tumor protection, and reduce activity of PD-1 expressing tumor-infiltrating effector CD4 and CD8 T cells." (PMID 28669079, 2018). "Considering we saw significantly greater tumor growth in our CD4+ vs. CD8+ depletion studies, we suspect the mechanism is likely the former." (PMID 30294332, 2018). "One study used a transplantable tumor model to determine that CD4+ T cells negatively regulated tumor rejection." (PMID 29973936, 2018). "Overall, we demonstrated the presence of tumor-specific CD4+ memory T cell responses against 3 neopeptides, IL-1βS230F, HELZ2V241M and MLL2A4802S." (PMID 30459932, 2018). "We then characterized the tumor Ag-specific CD4+ T cell response at ES and AS using gene expression profiling on total Marilyn cells from TdLN 7 days after transfer." (PMID 29844317, 2018).
tumor (continued). "Delivery of the tumor antigens by MVs also modulate cross-presentation of those tumor glycosylated antigens such as MUC1 that are thought to induce only a tolerogenic CD4+ T cell response, although being relevant for tumor targeting." (PMID 30455687, 2018). "In the same study, CCR5-positive DCs were attracted to the tumor site and were then licensed by CD4 T cells prior to the generation of CD8 T cell immunity." (PMID 29032503, 2018). "We also examined Tregs and found that the absolute number and percentage of CD4+Foxp3+ T cells in tumours were increased, but the CD8+/Treg ratio was significantly higher after treatment with vvDD-IL-2-RG compared to other virus treatment." (PMID 30410056, 2018). "We investigated impact of treatment on proliferation and apoptosis of effector CD8+ T cells and immunosuppressive CD4+Foxp3+ Tregs, as well as effector cytokines and chemokines in tumor and peripheral tissues." (PMID 30400822, 2018). "Transduced CD4+ T cells can also be activated by interaction with PD-L2, another ligand of PD-1, expressed on antigen-presenting cells present in the tumor microenvironment." (PMID 30214445, 2018). "In the present study, elevated Notch1 mRNA expression was found in both peripheral and tumor-resident CD4+ T cells in lung adenocarconoma patients." (PMID 30473538, 2018). "TLR-3 stimulation caused functional changes in TAMs, including increased phagocytic activity and upregulation of CD80 and CD86 expression with subsequent induction of CD4 T cell proliferation and tumor regression." (PMID 30420856, 2018). "It was demonstrated that mice with advanced MM expressed higher levels of PD-1 on both CD8+ and CD4+ T cells compared to non-tumor bearing mice and the percentages of PD-1+ T cells correlated with the amount of tumor burden." (PMID 30319648, 2018). "In this study, we found that LBP treatment inhibited the increase of CD4+ CD25high Tregs in tumor tissue, as well as the secretion of IL-10 and TGF-β1 in serum." (PMID 29967800, 2018). "For example, CT26 tumor has relatively higher frequency of CEACAM1+CD4 T cells compared to MBT2 or MC38." (PMID 30349641, 2018). "As expected, we observed strong enrichment for CTLs, Tregs and B-lymphocytes in hot tumours pan-cancer, while CD4-effectors, NK cells, eosinophils and CAFs were enriched in immune cold tumours." (PMID 30104673, 2018). "We further found a correlation between the frequencies of CD103+CD8+ and CD103+CD4+ in both the lung and tumor." (PMID 30505306, 2018). "Activation by toll-like receptor 7 (TLR7) ligand reverses pDC immunosuppressive function to such an extent that their administration to melanoma patients induces tumor-specific CD4+ and CD8+ T-cell responses." (PMID 29619026, 2018). "This endows them with the ability to present their own tumour antigens to CD4+ Th cells in vivo and to trigger potent and protective anti-tumour adaptive immune responses in both the CD4+ and CD8+ T-cell compartments." (PMID 29385169, 2018). "PD-L1 tumor cell expression was detected in 20/125 (13.8%) cases, which correlated with higher levels of PD-1, CD4, CD8 and HIF-2α expression." (PMID 30144808, 2018). "While ablation of CD4+ and CD8+ T cells had no impact on PDAC generation and persistency, this was different upon δTCR knock out: γδT cell deletion increased CD8+ CTL and CD4+ Th1 tumor infiltration, and skewed CD4+ differentiation toward the Th1 type." (PMID 30158932, 2018). "In turn, a report on 375 BTC patients, including 69 GBC samples, indicated that GBC patients with intraepithelial tumor-infiltrating CD4+ and CD8+ T cells showed significantly longer overall survival." (PMID 29499656, 2018). "We also show that when combined with OMVs decorated with the EGFRvIII B cell epitope or with OMVs carrying five tumor-specific CD4+ T cells neoepitopes, mD8-FAT1 OMVs conferred robust protection against tumor challenge in C57bl6 and BALB/c mice, respectively." (PMID 30416985, 2018).